CRP (C-reactive protein)
Diseases named in the same sentence as CRP in open-access papers (continued):
Sharing a sentence is not in itself a finding about the gene and the disease.
psychiatric disorder (continued). "One obvious way of enhancing our insight into the relationship between CRP and psychiatric disorders is to explore to what extent CRP is associated also with other aspects of brain function, including both other psychiatric disorders and normal personality traits." (PMID 18384670, 2008). "Future Directions: The integration of psychiatric scales (e.g., PHQ-9, GAD-7) with inflammatory biomarkers (CRP, IL-6) could improve diagnostic specificity, enabling differentiation between primary psychiatric disorders and inflammation-driven secondary conditions." (PMID 40218134, 2025). "Nevertheless, increasingly accurate assays such as high-sensitivity CRP (hs-CRP) are making this marker a more important research tool and potential support for the diagnosis and treatment of psychiatric disorders." (PMID 40872604, 2025). "In the field of psychiatry, an increasing body of research suggests a link between elevated CRP levels and psychiatric disorders such as depression, schizophrenia and bipolar disorder." (PMID 40872604, 2025). "In conclusion, adolescent psychiatric disorder diagnoses were associated with elevated levels of MMP-9, IL-6, and CRP and with inhibitory control dysfunction." (PMID 40219625, 2025). "This is supported by the fact that 18 of the loci that we found to be overlapping between MDD and total WBC were also identified in a recent conjFDR study investigating the genetic overlap between the acute phase protein CRP and psychiatric disorders." (PMID 41306196, 2025). "Measures of inflammation, such as C-reactive protein, have applications in many psychiatric disorders." (PMID 38824136, 2024). "Other risk factors mentioned in the literature include having more than five early symptoms, early dyspnea, prior psychiatric disorders, and specific biomarkers such as D-dimers, C-reactive protein, and lymphocyte count." (PMID 38468999, 2024). "This study further demonstrated that patients with psychiatric disorders have a considerably higher CRP level than the control group." (PMID 37803327, 2023). "Our study confirmed the interaction role of mitochondrial function and inflammatory cytokines (CRP) in the neuropathophysiological of psychiatric disorders." (PMID 37344456, 2023). "Regardless of the underlying mechanism, these findings collectively advocate further investigation of the direct and indirect effects of CRP on neuronal integrity to further reconcile the impact of CRP levels on cortical structure and psychiatric disorders." (PMID 36075890, 2022). "Among the studies included in the present systematic review, only three studies investigated CRP as a biomarker to differentiate psychiatric disorders." (PMID 35163538, 2022). "The inferred effect of CRP on different psychiatric disorders was particularly interesting given that there was evidence of an odds-decreasing effect on AN, OCD, and SZ, while the opposite is true for MDD." (PMID 35385317, 2022). "Further studies are eager to confirm our findings and clarify the more detailed mechanism of gut microbiome × CRP interaction in psychiatric disorders." (PMID 34481527, 2021). "Our data confirm that in patients with psychiatric disorders, C-reactive protein serum concentration is a relevant and important predictor of Trail-Making Test B performance, measuring cognitive flexibility." (PMID 33023087, 2020). "Various psychiatric disorders were investigated in a study assessing CRP in 599 admissions in a psychiatric catchment area." (PMID 30766494, 2018). "(III) In multiple studies elevations of CRP and/or proinflammatory cytokine levels were shown to return to normal when the psychiatric disorder was treated." (PMID 29181395, 2017). "The activation of these innate immune mechanisms, including proinflammatory cytokines, such as IL-1, IL-6, TNF-α, and CRP, may contribute to the development of psychiatric disorders." (PMID 38742123, 2024).
psychiatric disorder (continued). "This CSF panel includes interleukin (IL)-1β, IL-6, IL-8, IL-10, C-reactive protein (CRP), and tumor necrosis factor-alpha (TNF-α); inflammatory cytokines that have been linked to neuropsychiatric symptoms occurring in neurological and psychiatric disorders." (PMID 38336728, 2024). "According to further data, the neuroprotective effect of vitamin D on the brain might be also due to its ability to lower plasma C-reactive protein in patients with psychiatric disorders and to modulate inflammation by suppressing pro-inflammatory cytokines." (PMID 37109412, 2023). "For example, a large cohort study showed that both C-reactive protein (CRP) and leukocytes were significantly associated with both negative and positive symptoms in patients with psychiatric disorders." (PMID 37076806, 2023). "Furthermore, the literature has also focused on inflammatory mediators including C-Reactive Protein (CRP) and different cytokines, as potential biomarkers in psychiatric disorders, but with regard to SAD the available data is so far limited." (PMID 36614278, 2023). "Conceivably, sleep disturbance could increase inflammation-mediated effects in psychiatric disorders, as indicated by increasing concentrations of CRP through inflammatory and depressive pathways." (PMID 35821205, 2022). "The results suggested that elevated CRP levels might be a transdiagnostic biomarker in different psychiatric disorders, although multiple confounders might explain the presence of elevated CRP levels in a substantial portion of psychiatric patients." (PMID 35163538, 2022). "Therefore, CRP has a very promising potential in being a clinical biomarker for psychiatric disorders." (PMID 34884840, 2021). "It is possible that clinically-determined psychiatric disorders may show interaction effects with CRP." (PMID 28694011, 2017). "It remains a question for future research whether statin therapy might induce significant improvement in cognitive symptoms among those already diagnosed with psychiatric disorder, possibly by reducing circulating CRP concentration." (PMID 28694011, 2017). "The proportion of patients with any psychiatric disorders did not moderate the associations between childhood trauma and CRP (t=0.02, P=0.98, I2res=74.0%, τ2=0.007), IL-6 (t=0.23, P=0.82, I2res=48.5%, τ2=0.006) or TNF-α (t=0.54, P=0.61, I2res=42.7%, τ2=0.01)." (PMID 26033244, 2016). "Genotyping patients for IL6R rs2228145 while measuring their IL6 and CRP levels could be useful tools as non-specific diagnostic markers of alcohol- addicted patients with comorbid psychiatric disorders." (PMID 38275640, 2023). "Some studies highlighted that the long COVID syndrome could be associated with risk factors such female sex, more than five early symptoms, early dyspnea, prior psychiatric disorders, and specific biomarkers (e.g., D-dimer, CRP, and lymphocyte count), although more research is required." (PMID 35682394, 2022). "Meanwhile, the function of vitamin D may be attributed to its neuroprotective effect on the brain, as it has been proved that vitamin D is able to lower plasma C-reactive protein in patients with psychiatric disorders and modulate inflammation by suppressing proinflammatory cytokines." (PMID 35979473, 2022). "Of note, a recent systematic review and meta-analysis of 21 studies found that elevated CRP was associated with increased risk of suicidality, and particularly suicidal ideation, in individuals with psychiatric disorders, including those with affective and non-affective psychoses." (PMID 34704078, 2021). "However, the biological mechanism of CRP affecting the development of psychiatric disorders remains largely unknown now." (PMID 34481527, 2021). "Moreover, recent studies have also indicated that young patients (<18 years), with psychiatric disorders, may also have increased levels of CRP." (PMID 32997440, 2020).
psychiatric disorder (continued). "If the CRP level is between 50 and 200 mg/L and the patient not allergic to penicillin, two criteria must be added to obtain a risk factor of 33%: mandibular molar infection and psychiatric disorders." (PMID 33266250, 2020). "Additionally, the association between inflammation, as indicated by serum CRP levels, and psychiatric disorders has been studied, and some studies using serum CRP have shown that chronic inflammation may exert a significant negative impact on quality of life." (PMID 30186371, 2018). "Furthermore, alterations in cytokine secretion, such as increased levels of the inflammatory markers interleukin-6, TNF-a, and C-reactive protein, which contribute to dysfunctional immune responses, is another possible mechanism by which exposure to psychiatric disorders may be related to CRC risk." (PMID 41530201, 2026). "Recent studies showed that blood biomarkers have been used to predict health status in individuals with psychiatric disorders and OB, including the interleukins (IL-6, IL-10), tumor necrosis factor alpha (TNF-α), and C-reactive protein (CRP)." (PMID 39752432, 2025). "We have extended this area of research by comparing serum CRP levels, using a PRS-CRP including 47 SNPs, and investigating psychiatric disorders as well as cognition." (PMID 33517931, 2021). "Previous studies noted higher blood levels of inflammatory biomarkers (including IL-6, IL-1β, TNF-α, and CRP) in people with mental illness who have suicidal attempts in comparison to healthy controls or non-suicidal people with mental illness." (PMID 39882160, 2024). "C-reactive protein (CRP), tumor necrosis factor (TNF), soluble TNF receptor 1 (sTNFR1) and interleukin-6 (IL-6) are among the most frequently investigated inflammatory markers in the field of severe mental illness and exercise research." (PMID 37265560, 2023). "Recently published systematic review and meta-analysis evaluated the peripheral levels of pro-inflammatory markers including IL-1β, IL-6, TNF-α, and CRP between the elderly with AD and controls without any psychiatric disorder." (PMID 31277647, 2019). "The values for psychiatric disease, cerebrovascular accidents, polypharmacy, emergency surgery, hospitalization, the preoperative and postoperative SIIs, the NLR, the PLR, and the postoperative CRP were significantly higher in the POD group (p < 0.01) before and after matching." (PMID 40572710, 2025). "Finally, using a wider selection of inflammatory markers, rather than being limited to only CRP and IL-6, will also help in understanding which inflammatory pathways are important in the context of psychiatric disorders." (PMID 36277463, 2022). "This study also replicates and extends the literature on the relationship between neuroticism, the L/A ratio, adiponectin, CRP, IL-6 and TNF-α by focusing on previously unaddressed populations: young adults with and without psychiatric disorders." (PMID 33963214, 2021). "For example, studies have found higher levels of inflammatory markers including interleukin 6 (IL-6), a multifunctional cytokine, and C-reactive protein (CRP), an acute phase protein, among clinical patients with psychiatric disorders compared with individuals without these disorders." (PMID 30987624, 2019).
immune dysfunction (85 papers, 2013 to 2026). "This has stimulated epidemiological assessment of several biomarkers of inflammation and immune dysfunction, including C-reactive protein (CRP), interleukin-6 (IL-6) and D-dimer and their associations with age-related morbidity and HIV infection." (PMID 23994067, 2013). "First, an increase of CLR levels manifests as two parts: hyperactivation of the inflammation response, indicated by CRP elevations and immune disorders, indicated by decreased lymphocyte counts." (PMID 40976128, 2025). "Higher CRP and IL-6 levels in this group align with prior research linking immune dysfunction to muscle wasting and reduced physical resilience." (PMID 40277851, 2025). "Levels of inflammatory biomarkers, C-reactive protein (CRP) and procalcitonin (PCT), have been associated with systemic infection in patients with several immune dysfunctions." (PMID 23374857, 2013). "Thus, future studies should also focus on the potential of the CRP conformation for immunomonitoring during inflammatory processes, presumably unveiling early signs of immune dysfunction before onset of organ damage and failure." (PMID 39773175, 2025). "For example, detailed data on immune diseases, anti-inflammatory drugs and C-reactive protein." (PMID 36937901, 2023). "However, elevated C-reactive protein (CRP, 33 mg/L), erythrocyte sedimentation rate (ESR, 57 mm/hr), and ferritin (442.8 μg/L) suggest persistent systemic inflammation, possibly linked to chronic infection or immune dysfunction." (PMID 39871834, 2024). "Notably, in the subset of ALS defined as having innate immune dysfunction (elevated CRP), the median survival in the placebo group of 28.2 months was extended to 42.7 months in the NP001 treatment group and to 45.5 months in patients with low creatinine levels." (PMID 39457680, 2024). "A natural history study of ALS performed in Sweden showed a clear relationship between age and CRP, with CRP increasing the longer the ALS patient had the disease, especially in those patients with innate immune dysfunction." (PMID 40362586, 2025). "Acute phase proteins (APPs) such as C-reactive protein (CRP), haptoglobin (HP) and serum amyloid A (SAA) were secreted by hepatocytes and served as a crucial role in the etiopathogenesis of immune diseases." (PMID 36932457, 2023). "Biomarkers such as C-reactive protein (CRP), interleukin-6 (IL-6), and tumor necrosis factor-alpha (TNF-α) have been shown to correlate with systemic inflammation and immune dysfunction, which may play a role in the development of GI side effects." (PMID 39860995, 2025). "HF patients with low levels of C-NLR (i.e., low levels of CRP and/or NLR) have a better prognosis, indicating that inflammatory conditions and immune disorders may worsen the prognosis of HF patients." (PMID 38233747, 2024). "Newer high‐sensitivity assays can measure CRP levels in the 0.01–10 mg/L range, that is hs‐CRP, and can therefore quantify low‐grade systemic inflammation in the absence of obvious systemic inflammation or immune disorders." (PMID 36478511, 2023). "Additionally, the plasma EBV DNA load was positively correlated with the CRP level, suggesting that children with EBV-HLH suffer from multiple organ damage and severe immune dysfunction, as well as severe inflammatory reactions." (PMID 33413556, 2021). "Interestingly, inflammatory mediators such as CRP, TNF-α, IL-1ra, IL-6, IL-8, and IL-10 have been identified to be part of both: age-related diseases and trauma-induced immune dysfunction." (PMID 32258173, 2020). "However the CRP and WCC were unchanged, and we previously showed immune dysfunction in AD persisted throughout hospital admission." (PMID 28859868, 2018). "Moreover, these five deceased patients were characterized by abnormally low CRP levels and tremendous increase in LDH levels, which may be the result of other pathophysiological disorders, including disorders of the immune system, liver damage and haemolytic anemia." (PMID 36291697, 2022).
immune dysfunction (continued). "Corticosteroids group had lower lymphocyte count and higher levels of CRP and lactate dehydrogenase at hospital admission than non-corticosteroids group, indicating a propensity in prescribing corticosteroids to patients with more severe immune dysfunction and inflammatory response." (PMID 33172477, 2020). "CRP, PCT and IL-6 all showed significant increases in non-immune diseases than IM and immune diseases, with the value of 18.8 ± 1.4 mg/L (p<0.001), 1.5 ± 0.4ng/L (, p=0.001), and 121.4 ± 22.5pg/mL (, p<0.01), respectively." (PMID 37026057, 2023).
respiratory disease (84 papers, 2008 to 2026). "• Elevated CRP, decreased lymphocyte counts, and decreased monocyte counts at admission are associated with severe respiratory disease." (PMID 41989596, 2026). "Univariate analysis showed that CONUT scores; respiratory diseases; stent types; preoperative Hb, CRP, PT, and Fb levels were risk factors for death." (PMID 38751736, 2024). "After excluding any respiratory disease, the association between B‐Eos count, FeNO or CRP, and non‐respiratory diseases was analyzed in multivariate models and multicollinearity was tested." (PMID 34123365, 2021). "Various cytokines, such as IL2, IL4, IL6, IL8, and TNFα, and other inflammatory markers, such as intercellular adhesion molecule (ICAM) 1, soluble P-selectin, and CRP, have previously been associated with metal exposure or respiratory diseases." (PMID 25272992, 2014). "Furthermore, we compared B‐Eos count with FeNO and CRP regarding the association with non‐respiratory disease." (PMID 34123365, 2021). "The association with respiratory disease related mortality remained highly significant in multivariate models which included smoking as well as markers of severity and disease activity such as rheumatoid factor, nodular disease, and C-reactive protein (CRP)." (PMID 23031278, 2012). "In one of the patient the transitional rise of CRP was associated with a respiratory disease." (PMID 21197073, 2010). "The observed modification of the FEV1/AAT association by smoking and hormonal factors as well as by CRP-adjustment may reflect the dual role of AAT as a respiratory disease biomarker." (PMID 18439253, 2008). "Previous studies showed an association between GIPR and C-reactive protein levels and ITPKA was found to be related to respiratory system diseases, while PIK3C2B was reported to be associated with lung function." (PMID 40251596, 2025). "Univariate analysis revealed that CONUT scores; respiratory diseases; stent types; preoperative Hb, preoperative CRP, preoperative PT, and preoperative fibrinogen levels were risk factors for death." (PMID 38751736, 2024). "Elevated CRP levels have been observed in various respiratory diseases, and this result is useful for assisting diagnosis and monitoring." (PMID 38250933, 2024). "In the Pre-Group, several patients received prophylactic antibiotic treatment due to elevated CRP levels, preterm births, and respiratory disorders." (PMID 37760722, 2023). "The analysis of the parameters that showed significant differences by groups in the two-factor model according to the diagnoses grouped by areas revealed only differences in relation to CRP in respiratory disorders, with higher values among the controls." (PMID 36013306, 2022). "High prevalence of SARS-CoV-2 plasma viral load was found related to increased respiratory disease severity, low lymphocyte counts, and increased inflammation markers such as C-reactive protein and interleukin (IL)-6." (PMID 35582503, 2022). "An in-depth analysis was run regarding, among other parameters, CRP levels accompanying various respiratory diseases, including the infectious." (PMID 36290272, 2022). "Different from Hb, CRP concentration exhibited a left-skewed distribution that was only significantly higher for aged patients and those diagnosed with diseases of the respiratory system." (PMID 34830693, 2021). "A high fiber diet clinically reduces mortality by respiratory diseases via modulating inflammatory mediators such as IL-8, IL-6, and C-reactive protein (CRP)." (PMID 33953641, 2021). "The aim of this investigation was to (a) evaluate the influence of non‐respiratory disease on B‐Eos count, FeNO, and CRP, and (b) to identify individual characteristics that are associated with B‐Eos count in healthy individuals." (PMID 34123365, 2021). "Respiratory disorders, high C-reactive protein level, and the need for transfusion were significantly associated with severity." (PMID 32435626, 2020).